IL37 (interleukin 37)
Diseases named in the same sentence as IL37 in open-access papers (continued):
Sharing a sentence is not in itself a finding about the gene and the disease.
Respiratory tract infection (2 papers, 2022 to 2024). An infection of the upper or lower respiratory tract. "Furthermore, vitamin D reduces the risk of respiratory tract infection through three mechanisms including, (i) maintaining tight junctions, (ii) killing enveloped viruses through cathelicidin, IL-37, and induction of defenses, and (iii) reducing the production of pro-inflammatory cytokines." (PMID 36276415, 2022).
rosacea (2 papers, 2024 to 2025). A chronic erythematous skin disorder that affects the face. "They observed increased IL-36 (52.2 vs. 33.0 pg/mL, p < 0.001) and decreased IL-37 (18.5 vs. 44.6 pg/mL, p < 0.001) and IL-38 (25.7 vs. 45.6 ng/L, p < 0.001) in rosacea patients compared with controls." (PMID 41373451, 2025). "Our study shows that a combination therapy comprising TCM and standard biomedical treatment is more effective in reducing clinical symptom and TCM syndrome scores, as well as the scores of the DLQI, EI, and IL-37 levels in patients with rosacea." (PMID 39175550, 2024).
skin cancer (2 papers, 2022 to 2023). "Our data confirmed the breakthrough discovery of IL‐37 in the progress of skin cancer." (PMID 36891351, 2023). "However, the immune effects and mechanism of IL‐37 in the skin cancer microenvironment remain unclear, as well as the role and mechanism of IL‐37 in DC tumor immunosurveillance." (PMID 36891351, 2023). "However, the specific molecular mechanism and role of IL‐37 in skin cancer remain unclear." (PMID 36891351, 2023). "In a word, our results highlight that IL‐37 as an inhibitor of tumor immune surveillance through modulating CD103+DCs and establishing an important link between metabolism and immunity as a therapeutic target for skin cancer." (PMID 36891351, 2023).
viral infections (2 papers, 2019 to 2023). "Further detailed research remains necessary to fully determine the possible functions of IL-37 in viral infections." (PMID 31736917, 2019). "However, the function of IL-37 in other viral infections, especially serious emergent and re-emerged infectious diseases, remains unclear." (PMID 31736917, 2019). "Protective effects of the negative immunoregulatory molecule interleukin-37 (IL-37) have been observed in various bacterial and viral infections." (PMID 37507743, 2023).
vitamin D deficiency (2 papers, 2013 to 2021). A nutritional condition produced by a deficiency of VITAMIN D in the diet, insufficient production of vitamin D in the skin, inadequate absorption of vitamin D from the diet, or abnormal conversion of vitamin D to its bioactive metabolites. "The results of this study revealed that vitamin D deficiency is associated with an increased expression of IL-33, IL-37, IL-6, TNF-α, TLRs, DAMPs, and MMPs, while vitamin D supplementation is associated with a decreased expression of the former." (PMID 34842603, 2021).
allergic contact dermatitis (1 paper, 2024). An inflammatory skin condition caused by an immune response to direct contact between the skin and an allergen. "However, IL-37 was found to be responsible for the anti-allergic contact dermatitis by regulation of Smad3 participation." (PMID 39065733, 2024).
aneurysm (1 paper, 2022). Bulging or ballooning in an area of an artery secondary to arterial wall weakening. "Correlation analysis revealed that IL-37 was positively correlated with IL-6, TNF-α, age, aneurysm diameter, and blood pressure." (PMID 35602104, 2022). "Correlation analysis showed that IL-37 was positively correlated with IL-6, TNF-α, age, aneurysm diameter, SBP, and DBP." (PMID 35602104, 2022). "IL-37 present in the peripheral environment of patients with AAA is speculated to also act as negative feedback to regulate inflammation and delay aneurysm progression." (PMID 35602104, 2022).
attention deficit-hyperactivity disorder (1 paper, 2025). A disorder characterized by a marked pattern of inattention and/or hyperactivity-impulsivity that is inconsistent with developmental level and clearly interferes with functioning in at least two settings (e.g. at home and at school). "Many neurodevelopmental conditions, such as attention deficit hyperactivity disorder, intellectual disability, and cerebral palsy, are associated with inflammatory processes that may be targeted through IL-37-based interventions." (PMID 41425587, 2025).
autism (1 paper, 2025). Persistent deficits in social interaction and communication and interaction as well as a markedly restricted repertoire of activity and interest as well as repetitive patterns of behavior. "The finding of the mentioned studies demonstrated that IL-38 is deficient in this autism-relevant brain region, whereas IL-37 is elevated, suggesting a potential mechanistic correlation between neuroinflammation and fundamental autism symptoms." (PMID 41425587, 2025). "Mechanistic investigations into the molecular processes associated with IL-38 deficit and the dysregulation of IL-37 in autism constitute another essential research goal." (PMID 41425587, 2025). "The essential progression in understanding IL-38’s involvement in autism originated from the fundamental research conducted by Tsilioni and associates (2019; 2020), which provided the first direct evidence of altered IL-38 and IL-37 expression in brain tissue associated with autism." (PMID 41425587, 2025). "Genetic biomarkers may enhance patient selection, particularly polymorphisms in genes associated with IL-37 or IL-38 signaling, inflammatory control, or autism susceptibility." (PMID 41425587, 2025). "The functions of IL-38 and IL-37 during these initial developmental stages are predominantly unexplored; however, they may be vital for comprehending the cause of autism." (PMID 41425587, 2025). "Therapies based on IL-38 and IL-37 may signify a shift toward precision medicine strategies aimed at addressing the specific biological mechanisms associated with autism." (PMID 41425587, 2025). "Dysregulated production of IL-38 and IL-37 during this phase may induce excessive microglial activation, leading to abnormal synaptic pruning and altered neuronal connection patterns associated with autism." (PMID 41425587, 2025). "Although IL-38 and IL-37 show therapeutic potential, numerous challenges need to be resolved prior to their successful application in clinical settings for autism treatment." (PMID 41425587, 2025). "First Phase I clinical trials assessing the safety, tolerability, and pharmacokinetics of IL-38 or IL-37 in healthy volunteers and individuals with autism are essential preliminary steps." (PMID 41425587, 2025). "The dual effect renders IL-37 a compelling treatment target for tackling the intricate, multi-system characteristics of autism." (PMID 41425587, 2025). "Among the anti-inflammatory cytokines in this family, interleukin-38 (IL-38) and interleukin-37 (IL-37) are among the most recently identified and least comprehended members; yet, preliminary data indicates that they may play a significant role in neuroinflammation associated with autism." (PMID 41425587, 2025). "The involvement of IL-37 and IL-38 in modulating microglial activation is a crucial mechanism for regulating neuroinflammation in autism." (PMID 41425587, 2025). "The correlation between fluctuations in parallel IL-38 and IL-37 expression and autism development constitutes a pivotal domain for future research." (PMID 41425587, 2025). "The relationship between reduced NTR3/sortilin expression and increased IL-37 expression suggests complex interactions between different signaling systems in the autism brain." (PMID 41425587, 2025). "The discovery that the brain proactively seeks to mitigate neuroinflammation by upregulating anti-inflammatory mediators such as IL-37 offers a novel paradigm for comprehending autism and formulating treatment strategies." (PMID 41425587, 2025). "The co-expression of pro-inflammatory and anti-inflammatory mediators indicates a persistent inflammatory conflict inside the brain tissue of individuals with autism, with IL-37 possibly acting as an endogenous mechanism to regulate excessive inflammation." (PMID 41425587, 2025). "This upregulation of the shared receptor suggests that both pro-inflammatory (IL-18) and anti-inflammatory (IL-37) signaling pathways are enhanced in autism brain tissue." (PMID 41425587, 2025).
autism (continued). "We propose a “IL-37/IL-38 axis” model of immune regulation in autism by analyzing their convergent and divergent signaling routes: IL-37 through IL-18Rα/IL-1R8 and IL-38 through IL-36R/IL-1RAPL1." (PMID 41425587, 2025). "And investigate the molecular biology of cytokines IL-37 and IL-38, their expression profiles in autism, their interactions with other immune mediators, and the implications for future research and clinical applications." (PMID 41425587, 2025). "On the contrary, despite the chronic neuroinflammation associated with ASD, the study revealed a substantial increase in IL-37 expression (p=0.004) in the amygdala and dorsolateral prefrontal cortex of children with autism." (PMID 41425587, 2025). "The therapeutic possibilities of IL-38 and IL-37 research are particularly significant in consideration of the existing limitations in autism treatment." (PMID 41425587, 2025). "Extensive replication studies are critically required to validate the preliminary observations of decreased IL-38 expression in the brain tissue of individuals with autism, alongside the elevated levels of IL-37 in the brains of children diagnosed with ASD." (PMID 41425587, 2025). "Despite these obstacles, the potential of IL-37 and IL-38 cytokine research in autism is significant." (PMID 41425587, 2025). "Due to the intricate, multifactorial characteristics of autism, interventions utilizing IL-37 and IL-38 will probably be most efficacious when incorporated into combination or multimodal strategies." (PMID 41425587, 2025). "Research on IL-38 and IL-37 in autism will be enhanced by various technological innovations and methodological advancements." (PMID 41425587, 2025). "The emergence of IL-38/IL-37 as potential key players in autism pathophysiology has broader implications for autism research." (PMID 41425587, 2025). "The recognition of the IL-37/38 axis as a potential biomarker and therapeutic target signifies a transformative shift toward precision medicine strategies in autism therapy." (PMID 41425587, 2025). "Establishing suitable outcome measures capable of identifying clinically significant enhancements in autism symptoms after IL-38 or IL-37 treatment is essential for regulatory approval." (PMID 41425587, 2025). "The emergence of IL-38 and IL-37 as significant anti-inflammatory mediators in this environment places them as possible essential regulators of autism-related neuroinflammation." (PMID 41425587, 2025). "Longitudinal studies monitoring variations in IL-38 and IL-37 expression over time may elucidate the temporal dynamics of neuroinflammation in autism and pinpoint essential intervention periods." (PMID 41425587, 2025). "If IL-38/IL-37 transport fails in autism, therapeutic strategies might be needed to concentrate on improving barrier function, creating alternate delivery mechanisms, or directly targeting cerebral tissue with IL-38/IL-37 or their analogs." (PMID 41425587, 2025). "Furthermore, comprehending the interactions of IL-37 with various inflammatory mediators, neurotransmitter systems, and developmental processes in relation to autism will be essential for enhancing therapy strategies." (PMID 41425587, 2025). "Comprehensive inflammatory profiling of large autism cohorts may reveal subgroups that are most likely to benefit from IL-38/IL-37 therapy and facilitate the development of predictive algorithms for treatment response." (PMID 41425587, 2025). "IL-37 may preserve intestinal barrier integrity, so mitigating systemic inflammatory responses that can exacerbate neuroinflammation in autism." (PMID 41425587, 2025). "Besides contributing to its therapeutic potential, both IL-37 and IL-38 exhibit promise as biomarkers for the diagnosis and monitoring of autism treatment." (PMID 41425587, 2025). "Not all individuals with autism exhibit deficiencies in IL-38 or IL-37, and the severity of such deficiencies can considerably vary among patients." (PMID 41425587, 2025).
autism (continued). "The discovery of IL-38 and IL-37’s potential relevance to autism came from ground-breaking research by Tsilioni and colleagues (2019, 2020), who demonstrated decreased IL-38 expression in the amygdala of children with ASD, coupled with its ability to inhibit microglial inflammatory responses." (PMID 41425587, 2025). "In autism, this regulating system may be compromised by chronic inflammatory stimulation, resulting in persistent neuroinflammation despite elevated IL-37 expression." (PMID 41425587, 2025). "Additionally, they observed earlier that, increased expression of IL-37 in autism brain tissue can be understood as part of a broader compensatory anti-inflammatory response that attempts to counteract chronic neuroinflammation." (PMID 41425587, 2025). "Furthermore, one of the most important findings regarding IL-37’s role in autism relates to its ability to modulate microglial function and inflammatory responses." (PMID 41425587, 2025). "Single-cell sequencing technologies could provide unprecedented insights into cell-type-specific IL-38 or IL-37 expression patterns in autism brain tissue." (PMID 41425587, 2025). "While, the tissue distribution of IL-37 is also broad, with expression detected in various immune and non-immune cells, including macrophages, dendritic cells, epithelial cells, and importantly for autism research, microglial cells in the central nervous system." (PMID 41425587, 2025). "Positron emission tomography (PET) tracers specific for IL-38 or IL-37 or their receptors could enable direct visualization the IL-38 and IL-37 system in the autism brain, and measurement of neuroinflammation and help to identify patients with the highest levels of brain inflammation." (PMID 41425587, 2025). "Consequently, IL-37 and IL-38 may function as both therapeutic agents and integral elements of personalized, multimodal therapy strategies for autism." (PMID 41425587, 2025). "The significant potency of IL-38, together with the broad anti-inflammatory properties of IL-37 and its natural presence in the human body, indicates that therapies utilizing these cytokines may offer effective and safe therapeutic alternatives for individuals with autism." (PMID 41425587, 2025). "Besides, another study reported an increased IL-37 expression—particularly in the amygdala and dorsolateral prefrontal cortex—which represent critical areas for social behavior, emotional processing, and executive function, all domains significantly affected in autism." (PMID 41425587, 2025).
breast adenocarcinoma (1 paper, 2026). "This review aims to study the role of MCs accumulated in the stroma of breast adenocarcinoma in relation to secreted anti-inflammatory cytokines, such as IL-37 and IL-38." (PMID 41596472, 2026).
brucellosis (1 paper, 2023). Brucellosis is a bacterial infection that spreads from animals to people via unpasteurized dairy products or by exposure to contaminated animal products or infected animals. "Importantly, serum IL-37 concentration was lower in patients with brucellosis than in healthy controls." (PMID 36326182, 2023). "In addition, IL-37 level was strongly reduced in acute brucellosis than in chronic brucellosis." (PMID 36326182, 2023).
calcification (1 paper, 2024). Process by which organic tissue becomes hardened by the physiologic deposit of calcium salts. "We developed valvular calcification in hamsters fed a HCHF diet, examined the relationship between elevated AGE-LDL and hamster valvular calcification, and tested the hypotheses that the impact of IL-37 on valvular calcification was due to the regulation of AGE-LDL in hamsters." (PMID 38840067, 2024).
candidiasis (1 paper, 2014). Infection with the organism Candida. "We observed that mice overexpressing IL-37 were more susceptible to invasive candidiasis, due to the inability to control fungal growth in the kidney during infection." (PMID 25620965, 2014). "The effect of the anti-inflammatory cytokine interleukin-37 (IL-37) on host defense against Candida infections remains unknown." (PMID 25620965, 2014).
cardiomyopathy (1 paper, 2024). A disease of the heart muscle or myocardium proper. "Here we need to explore the underlying molecular mechanisms by which IL-37 exerts on mitochondrial protection against HG-induced cardiomyopathy." (PMID 38790051, 2024). "Besides, we and other researchers have shown that IL-37 could protect cardiomyocytes and endothelial cells from apoptosis by alleviating ROS stress, suggesting its possible involvement in the pathophysiology of hyperglycemia-induced cardiomyopathy." (PMID 38790051, 2024).
Cerebral ischemia (1 paper, 2019). Restriction of arterial blood supply to the brain associated with insufficient oxygenation to support the metabolic requirements of the tissue. "In IL-37tg mice, cerebral ischemia-reperfusion resulted in marked increases in plasma IL-37 (~9-fold) and brain IL-37 mRNA (~7,000-fold) at 24 h compared with sham-operated IL-37tg mice." (PMID 31061403, 2019).
childhood asthma (1 paper, 2018). "A study on childhood asthma showed that levels of IL-37 in serum and expression level of IL-37 mRNA in induced sputum (IP) in asthmatic children were lower than those in the normal controls and were related to the severity of the disease." (PMID 29805973, 2018).
cholestasis (1 paper, 2021). Impairment of the bile flow caused by obstruction within the liver, or outside the liver in the bile duct system. "Therefore, we speculate that intracellular IL-37, as expressed in IL-37tg mice, plays a more dominant role in modulating cholestasis-induced liver inflammation and fibrosis after BDL than extracellular IL-37." (PMID 33746950, 2021).
chronic asthma (1 paper, 2022). An asthma that is characterized by the development of persistent airway inflammation and recurrent attacks of breathlessness and wheezing, which vary in severity and frequency. "We aimed to explore the effect and mechanism of IL-24 on EMT and to verify whether IL-37 could alleviate IL-24-induced EMT in chronic asthma." (PMID 36100847, 2022). "Similarly, the in vivo results showed that IL-24 was overexpressed in the airway epithelium of an HDM-induced chronic asthma model, and IL-24 silencing or IL-37 treatment could reverse EMT biomarker expression." (PMID 36100847, 2022).
chronic endometritis (1 paper, 2026). A non-granulomatous or granulomatous chronic inflammation of the endometrium. "Interleukin-37 (IL-37) is an anti-inflammatory cytokine with an undefined role in chronic endometritis (CE)." (PMID 41751489, 2026).
chronic rhinosinusitis with nasal polyps (1 paper, 2021). A type of chronic rhinosinusitis that is characterized by the presence of nasal polyps. "IL-37 mRNA and protein expression is substantially upregulated in nasal epithelial cells of patients with chronic rhinosinusitis with nasal polyps (CRSwNP), compared with control subjects who underwent septoplasty for anatomic variations and did not have other sinonasal diseases." (PMID 34248996, 2021).
coeliac disease (1 paper, 2024). "It is speculated that IL-37 may protect individuals from food allergy and/or coeliac disease." (PMID 39206201, 2024). "Following an extensive literature search, no published data on the role of IL-37 in food allergy or coeliac disease has been found." (PMID 39206201, 2024).
Cognitive impairment (1 paper, 2022). Abnormal cognition is characterized by deficits in thinking, reasoning, or remembering. "Injection of recombinant IL-37 into WT mice showed restoration of cognitive deficits and reduced release of pro-inflammatory cytokines after IL-1β-mediated immunostimulation." (PMID 36040311, 2022).